RNU6-704P (RNA, U6 small nuclear 704, pseudogene)
Gene: Small nuclear RNA gene on chromosome 1 (200,933,345 to 200,933,447, reverse strand). Ensembl gene ENSG00000201032.
Homologues: Orthologues: chimpanzee U6 (99% identical), macaque U6 (95% identical), pig U6 (81% identical), rabbit U6 (73% identical), rabbit U6 (68% identical), mouse Gm25008 (67% identical), dog U6 (64% identical). Paralogues in human: RNU6-1209P (84% identical), RNU6-1329P (83% identical), RNU6-183P (83% identical), RNU6-434P (83% identical), RNU6-797P (83% identical), RNU6-812P (83% identical), RNU6-1091P (83% identical), RNU6-1145P (83% identical), RNU6-115P (83% identical), RNU6-181P (83% identical), RNU6-38P (83% identical), RNU6-393P (83% identical), and 1285 more.